NELFCD (negative elongation factor complex member C/D)
Description:
Essential component of the NELF complex, a complex that negatively regulates the elongation of transcription by RNA polymerase II. The NELF complex, which acts via an association with the DSIF complex and causes transcriptional pausing, is counteracted by the P-TEFb kinase complex. (Microbial infection) The NELF complex is involved in HIV-1 latency possibly involving recruitment of PCF11 to paused RNA polymerase II.
Synonyms: TH1; TH1L; HSPC130; NELF-C; NELF-D
Tractability: Small molecule: a structure with a bound ligand is known. PROTAC: ubiquitination databases record sites on it; its protein half-life has been measured.
Gene: Protein-coding gene on chromosome 20 (58,981,208 to 58,995,133, forward strand). Ensembl gene ENSG00000101158.
Subcellular location: Nucleus
Subcellular location (Human Protein Atlas): Nuclear bodies; Nucleoplasm; Cytosol; Vesicles
Pathways (Reactome):
Disease: Abortive elongation of HIV-1 transcript in the absence of Tat; Formation of HIV elongation complex in the absence of HIV Tat; Formation of HIV-1 elongation complex containing HIV-1 Tat; Formation of the HIV-1 Early Elongation Complex; HIV elongation arrest and recovery; Pausing and recovery of HIV elongation; Pausing and recovery of Tat-mediated HIV elongation; Tat-mediated HIV elongation arrest and recovery; Tat-mediated elongation of the HIV-1 transcript
Gene expression (Transcription): Formation of RNA Pol II elongation complex; Formation of the Early Elongation Complex; RNA Polymerase II Pre-transcription Events; RNA Polymerase II Transcription Elongation
Gene Ontology:
Molecular function: protein binding; RNA polymerase inhibitor activity; RNA binding
Biological process: negative regulation of transcription elongation by RNA polymerase II; transcription pausing by RNA polymerase II; negative regulation of DNA-templated transcription
Cellular component: membrane; NELF complex; nuclear body; nucleoplasm; nucleus
Genetic constraint (gnomAD): Loss-of-function variants: 41 observed, 61.7 expected, observed/expected ratio (o/e) 0.66, 90% interval 0.52 to 0.86. The upper end of that interval is the gene's LOEUF score, 0.86, which puts it in group 3 of 6, group 1 being the genes least tolerant of losing a copy. Missense variants: 488 observed, 693.48 expected, observed/expected ratio (o/e) 0.7, 90% interval 0.65 to 0.76. Synonymous variants: 275 observed, 276.74 expected, observed/expected ratio (o/e) 0.99, 90% interval 0.9 to 1.1.
Homologues: Orthologues: chimpanzee NELFCD (100% identical), macaque NELFCD (99% identical), dog NELFCD (99% identical), pig NELFCD (99% identical), guinea pig NELFCD (98% identical), mouse Nelfcd (98% identical), rat Nelfcd (98% identical), rabbit NELFCD (96% identical), zebrafish nelfcd (91% identical), tropical clawed frog nelfcd (86% identical), Drosophila melanogaster TH1 (54% identical).
Diseases named in the same sentence as NELFCD in open-access papers:
NELFCD is named in the same sentence as 196 diseases in open-access papers, as found by Europe PMC text mining. Sharing a sentence is not in itself a finding about the gene and the disease. The quoted sentences say what the papers report.
colorectal cancer (2 papers, 2024). A primary or metastatic malignant neoplasm that affects the colon or rectum. "Similarly, it has also been proven that NELFCD, as a transcription factor, is up-regulated in colorectal cancer tissues and plays a carcinogenic role." (PMID 38212657, 2024).
colorectal tumors (1 paper, 2026). "Here, we find that expression of NELFCD, a known negative transcription elongation factor, is upregulated in colorectal tumors." (PMID 41721097, 2026).
cancer (25 papers, 2012 to 2026). A tumor composed of atypical neoplastic, often pleomorphic cells that invade other tissues. "For instance, genes such as SAC3D1, NELFCD, and TAF9 (TATA-box binding protein associated factor 9) were implicated in the DNA repair pathway and are associated with survival in some cancers." (PMID 33477315, 2021).
NELFCD also shares sentences with these, for which no sentence is quoted: infection (99 papers); tumor (70); asthma (33); psoriasis (19); autoimmune disease (18); COVID-19 (15); tuberculosis (12); colitis (11); allergic disease (10); viral infection (10); influenza (8); sarcoidosis (8); allergic asthma (7); Anxiety (7); atopic dermatitis (7); breast carcinoma (6); Granuloma (6); malaria (6); Obesity (6); Arthritis (5); depression (5); brucellosis (4); diabetes (4); fungal infection (4); helminth infections (4); lung carcinoma (4); Miscarriage (4); pneumonia (4); Sepsis (4); type 1 diabetes (4).
A further 163 diseases each share a sentence with NELFCD in 3 papers or fewer.